IGFBP1 (insulin like growth factor binding protein 1)
Diseases named in the same sentence as IGFBP1 in open-access papers (continued):
Sharing a sentence is not in itself a finding about the gene and the disease.
unstable angina (3 papers, 2017 to 2020). "We therefore hypothesized that the circulating IGFBP1 level might be associated with the extent of the atherosclerotic lesions and could be used as a biomarker reflecting the severity of coronary artery lesions in patients with unstable angina." (PMID 28316362, 2017). "In conclusion, as a regulator in the development of coronary plaques, circulating IGFBP1 showed a great promise in predicting the severity of coronary artery lesions in patients with unstable angina." (PMID 28316362, 2017). "In previous studies in non-pregnant study groups, the level of IGFBP-1 has been found to correlate with traditionally measured serum total HDL cholesterol in ischaemic heart disease, type 2 diabetic patients and healthy subjects and in patients with unstable angina." (PMID 32923723, 2020).
Abdominal obesity (2 papers, 2021 to 2025). Excessive fat around the stomach and abdomen. "Thus, currently, the relative importance of molecular traits such as IGFBP-1 remains uncertain in comparison with the mechanical effects of increased abdominal obesity in the development of esophageal adenocarcinoma." (PMID 40987470, 2025).
abnormal glucose tolerance (2 papers, 2020 to 2022). "In conclusion, this study suggests that the majority of subjects with low fasting IGFBP-1 and adiponectin levels benefit from bariatric surgery with improved insulin sensitivity and glucose tolerance as well as reduced risk factors for cardiovascular disease and future abnormal glucose tolerance." (PMID 32934313, 2020). "After adjustment, the lowest quartile of adiponectin, IGFBP-1 and IGFBP-2 associated independently with future abnormal glucose tolerance (AGT) in both genders in multivariate analyses." (PMID 36686443, 2022).
abortion (2 papers, 2024 to 2025). the ending of pregnancy by removing a fetus or embryo before it can survive outside the uterus. "Consistent with previous studies, we found that decidualization was impaired in abortion patients, as shown by abnormal morphology and downregulation of the decidual markers IGFBP1 and PRL." (PMID 38769534, 2024).
Alzheimer disease (2 papers, 2022). A progressive, neurodegenerative disease characterized by loss of function and death of nerve cells in several areas of the brain leading to loss of cognitive function such as memory and language. "In addition, patients with severe and moderate Alzheimer's disease demonstrated a progressive elevation in the expression levels of IGFBP1 protein in their blood profile." (PMID 35989938, 2022). "In addition, IGFBP-1, which was significantly lower in Dem-Alzheimer's disease compared with CN individuals, was also significantly lower in Dem-Alzheimer's disease compared with Dem-Other (fold-change = 0.63, P = 0.03), suggesting the change maybe unique to Alzheimer's disease pathology." (PMID 35800899, 2022).
chronic endometritis (2 papers, 2020 to 2024). A non-granulomatous or granulomatous chronic inflammation of the endometrium. "For instance, chronic endometritis is characterized by a modified gene expression profile involving proinflammatory mediators like IL11, IL17, TGF-β, CCL4, IGFBP1, and CASP8, contrasting with the gene expression profile observed in normal fertile women during the implantation window." (PMID 38927030, 2024).
colorectal adenoma (2 papers, 2012 to 2018). An adenoma that arises from the colon or rectum. "The aim of this study was to determine the associations of IGFBP-1, insulin, and C-peptide (a surrogate biomarker of pancreatic insulin secretion), with colorectal adenoma (adenomatous polyps) in the Diet and Health study IV, in a majority White cohort and whether these associations vary by gender." (PMID 22950808, 2012). "Few studies have evaluated IGFBP-1 and C-peptide or insulin in relation to colorectal adenomas and cancer and the results are inconsistent." (PMID 22950808, 2012). "Thus, IGFBP-1 levels may influence colorectal adenomas and cancer development via two mechanisms: inhibition of the proliferative actions of insulin and IGF, and promotion of apoptosis." (PMID 22950808, 2012).
endometrial polyp (2 papers, 2021 to 2025). A benign nodular lesion protruding above the surface of the endometrium. "To determine whether polypectomy influences the expression of implantation-related factors, we examined the effects of excision on the expression levels of the IGFBP1, IGFBP7, PTGS2, and CALR mRNAs in 27 patients with endometrial polyps." (PMID 34638846, 2021). "Specifically, the pre- and post-polypectomy groups had significantly different IGFBP-1 concentrations, with the IGFBP-1 levels found to be lower in the women with endometrial polyps than in the women without polyps." (PMID 39941173, 2025).
endothelial dysfunction (2 papers, 2021). In vascular diseases, endothelial dysfunction is a systemic pathological state of the endothelium (the inner lining of blood vessels) and can be broadly defined as an imbalance between vasodilating and vasoconstricting substances produced by (or acting on) the endothelium. "However, concentrations of tissue factors like IGFBP-1, uPA, and HGF were comparable to UE, suggesting less endothelial dysfunction in Sub2." (PMID 34893580, 2021).
esophageal adenocarcinoma (2 papers, 2021 to 2025). A malignant tumor with glandular differentiation arising predominantly from Barrett mucosa in the lower third of the esophagus. "Alternatively, IGFBP-1 may cause esophageal adenocarcinoma through IGF-1 intercellular transport and intracellular activity, which may not be captured by circulating IGF-1 levels." (PMID 40987470, 2025). "In our analysis, we found little evidence for a causal effect of IGF-1 directly on esophageal adenocarcinoma risk, suggesting that the biological mechanism linking IGFBP-1 and esophageal adenocarcinoma risk may be independent of its role regulating IGF-1." (PMID 40987470, 2025). "Finally, our analysis suggested that IGFBP-1 may mediate the effect of ASAT on esophageal adenocarcinoma." (PMID 40987470, 2025). "The combination of SLC26A9 with AP002478.1, BHLHA15, FFAR2, IGFBP1, KCTD8, and PHYHD1 was also identified as a gene signature for personalized prognosis prediction and targeted therapy of esophageal adenocarcinoma." (PMID 35008199, 2021). "However, we find novel evidence of IGFBP-1 having a potential molecular mediating role in the ASAT and esophageal adenocarcinoma relationship." (PMID 40987470, 2025).
fibrosis (2 papers, 2022 to 2024). the formation of excess fibrous connective tissue in an organ or tissue in a reparative or reactive process. "Our results show significantly increased serum levels of IGFBP-1 and -2 in mice with NAFLD and fibrosis." (PMID 38541155, 2024). "Linear regression models confirmed the predictive value of IGFBP-1, -2, and -7 for both NAFLD stages and fibrosis degree." (PMID 38541155, 2024). "For IGFBP-1, we observed differences in the serum related to both NAFLD and fibrosis." (PMID 38541155, 2024).
hepatoblastoma (2 papers, 2020 to 2021). Hepatoblastoma (HB) is a malignant hepatic tumor and is the most common pediatric liver cancer. "GATA4 is also highly expressed in most hepatoblastomas and correlates with a mesenchymal, migratory phenotype in hepatoblastoma cells by regulating the expression of ADD3, AHNAK, and IGFBP1." (PMID 33648545, 2021). "The IGFBP3 levels were very low or undetectable in human HCC samples compared with non‐neoplastic liver tissue which are 4‐ to 100‐fold higher than in HCC49 and IGFBP‐1 and IGFBP‐2 were also decreased in hepatoblastoma." (PMID 32798252, 2020).
melancholic depression (2 papers, 2016 to 2020). "The study demonstrated that in atypical depression the following molecules were altered as compared to melancholic depression: higher leptin, FABPa, complement C3, insulin, B2-microglobulin, ACE, and lower insulin-like growth factor-binding protein 1 and 2 (IGFBP1, IGFBP2) and mesothelin." (PMID 33255237, 2020). "No mediation was found for IGFBP1, ACE and B2M (comparison atypical and melancholic depression) and B2M, ANG2 and VWF (comparison atypical depression and controls)." (PMID 27404283, 2016).
nasopharyngeal carcinoma (2 papers, 2017 to 2020). A carcinoma arising from the nasopharyngeal epithelium. "Furthermore, high levels of serum IGFBP-1 were shown in patients with nasopharyngeal carcinoma (NPC) and associated with poor prognosis." (PMID 32526853, 2020).
nonalcoholic fatty liver disease (2 papers, 2013 to 2023). "The finding of lower serum IGFBP1 levels associated with nonalcoholic fatty liver disease suggests that increased IGFBP1 expression may be caused by alcohol consumption." (PMID 24152801, 2013).
osteosarcoma (2 papers, 2022). A usually aggressive malignant bone-forming mesenchymal neoplasm, predominantly affecting adolescents and young adults. "Also, GCT (32.90 ± 1.55) group expressed significantly lower level of IGFBP-1 compared to osteosarcoma (P=0.0005) and Ewing sarcoma (P=0.01) groups." (PMID 36713521, 2022). "In summary, our data suggested that IGF-1R, IGF-1, IGFBP-1, and IGFBP-3 levels are associated with bone tumor malignancy, metastasis, and recurrence that might serve as biomarkers for osteosarcoma and Ewing sarcoma recurrence." (PMID 36713521, 2022). "However, the relative expression levels of LYN, TNC, TGFB2, and IGFBP1 were significantly higher in the osteosarcoma group compared with the normal group (P < 0.05)." (PMID 35665757, 2022). "The patients with metastatic (50.46 ± 3.29) and recurrent (52.11 ± 3.29) osteosarcoma tumors produced a significantly higher level of IGFBP-1 compared to patients with non-metastatic (40.80 ± 2.66) (P=0.04) and non-recurrent (40.64 ± 2.53) (P=0.009) osteosarcoma tumors." (PMID 36713521, 2022).
ovarian clear cell adenocarcinoma (2 papers, 2020 to 2023). A malignant glandular epithelial neoplasm characterized by the presence of clear and hobnail cells. "In ovarian clear cell adenocarcinoma, IGFBP1 has specifically expressed in both protein level and mRNA level by using immunohistochemistry and in situ hybridization." (PMID 33282953, 2020). "IGFBP1 is specifically expressed in ovarian clear-cell adenocarcinoma." (PMID 37907850, 2023).
schwannoma (2 papers, 2020 to 2024). A benign, usually encapsulated slow growing tumor composed of Schwann cells. "Human schwannoma cells have been shown to release IGFBP1, which activates Src/FAK signaling in an integrin β1-dependent manner, mediating increased proliferation and cell–matrix adhesion." (PMID 39337558, 2024). "IGFBP1 has increased cell proliferation, cell-matrix adhesion, and regulate survival in schwannoma cells through the integrin β1/Src/FAK pathway." (PMID 33282953, 2020).
Sepsis (2 papers, 2013 to 2023). Sepsis is defined as life-threatening organ dysfunction caused by a dysregulated host response to infection. "The results showed that IGFBP1, IGFBP2, IGF2BP1, and WTAP were highly expressed in patients with advanced sepsis and m6A cluster B; IGFBP1, IGFBP2, and IGF2BP1 showed a significant positive correlation with Th17 helper T cells." (PMID 37330481, 2023). "IGFBP1, IGFBP2, IGF2BP1, and WTAP were highly expressed in patients with advanced sepsis and m6A cluster B. IGFBP1, IGFBP2, and IGF2BP1 were positively correlated with Th17 helper T cells." (PMID 37330481, 2023). "Based on the RF model and correlation analysis, IGFBP1, IGFBP2, IGF2BP1, WTAP, and METTL16 were screened out to accelerate the occurrence and development of sepsis by regulating m6A methylation and promoting immune cell infiltration." (PMID 37330481, 2023). "IGFBP1, IGFBP2, IGF2BP1, and WTAP were highly expressed in advanced sepsis patients, and the remaining 17 regulators were poorly expressed." (PMID 37330481, 2023). "IGFBP1, IGFBP2, IGF2BP1, WTAP, and METTL16 may accelerate the development of advanced sepsis by regulating m6A methylation modification and promoting immune cell infiltration." (PMID 37330481, 2023).
serous ovarian cancer (2 papers, 2010 to 2020). "A third set of samples that was restricted to serous ovarian cancer cases (44 SOC, 78 HA controls) was used to confirm the elevation of IGFBP1." (PMID 20559444, 2010).
stomach adenocarcinoma (2 papers, 2023). "In stomach adenocarcinoma, IGFBP1 is upregulated, but IGFBP2 and IGFBP6 are downregulated." (PMID 37088808, 2023).
vitamin D deficiency (2 papers, 2019 to 2022). A nutritional condition produced by a deficiency of VITAMIN D in the diet, insufficient production of vitamin D in the skin, inadequate absorption of vitamin D from the diet, or abnormal conversion of vitamin D to its bioactive metabolites. "Since IGFBP-1 is negatively correlated with size at birth, this finding would suggest that vitamin D supplementation could have a negative effect on fetal growth in women with prenatal vitamin D deficiency." (PMID 31071681, 2019).
acute coronary syndrome (1 paper, 2024). Signs and symptoms related to acute ischemia of the myocardium secondary to coronary artery disease. "In a study of individuals with acute coronary syndrome (n = 112, 26–83 y, 41% F), IGFBP-1 was positively associated with patient age and, in age-comparable patients, IGFBP-1 was increased in critical coronary artery disease." (PMID 39595651, 2024).
acute kidney injury (1 paper, 2021). Sudden and sustained deterioration of the kidney function characterized by decreased glomerular filtration rate, increased serum creatinine or oliguria. "IGFBP-1 expression is elevated in IgA nephropathy, FSGS, acute kidney injury (AKI) and CKD." (PMID 35002740, 2021).
adenoma (1 paper, 2012). A neoplasm arising from the epithelium. "On the other hand, we found a statistically significant association between higher levels of IGFBP-1 and reduced risk for adenoma in men (OR = 0.3, 95% CI 0.1-0.7, p-trend = 0.0007)." (PMID 22950808, 2012). "Individuals with high insulin concentrations also had a higher risk of adenomas (OR = 3.5, 95% CI 1.7-7.4), whereas higher levels of IGFBP-1 were associated with a reduced risk of adenomas in men only (OR = 0.3, 95% CI 0.1-0.7)." (PMID 22950808, 2012). "Based on these previous observations, we hypothesized that elevated IGFBP-1 is associated with reduced risk of adenomas and low apoptosis in normal mucosa." (PMID 22950808, 2012).
AIDS (1 paper, 2015). A syndrome resulting from the acquired deficiency of cellular immunity caused by the human immunodeficiency virus (HIV). "CSF IGFBP1 was higher in subjects with AIDS (P = 0.016) and alcohol dependence (P = 0.037)." (PMID 25890304, 2015).
alcoholic cirrhosis (1 paper, 2024). "In alcoholic cirrhosis, serum IGFBP1 levels was elevated when compared with controls." (PMID 38614964, 2024).
amenorrhoea (1 paper, 2021). "As an independent predictor of amenorrhoea, IGFBP-1 may act as a peripheral signal to the central control of the HPG axis, and mediate information on the availability of metabolic fuel for the control of reproductive function (given the direct inverse regulation of IGFBP-1 levels by serum insulin)." (PMID 34360982, 2021).
asthma (1 paper, 2020). "β-HEX’s positive association with IL-5/IL-13 (known promoters of the Th2 response), negative association with IGFBP-1 and IgG2, elevated stability in plasma, and low cost of measurement advocate for the use of β-HEX as a routine biomarker for severe asthma in pediatrics." (PMID 33036262, 2020).
ataxia telangiectasia (1 paper, 2014). Ataxia-telangiectasia is the association of severe combined immunodeficiency (affecting mainly the humoral immune response) with progressive cerebellar ataxia. "Both types of patients have increased serum IGF-1 and IGFBP-2 levels, and decreased serum IGFBP-1 levels; while only ataxia-telangiectasia patients have high serum insulin levels." (PMID 26331037, 2014).
Atrophy (1 paper, 2026). Any weakening or degeneration, especially through lack of use. "The diseased mice displayed splenic atrophy and systemic inflammation, with elevated serum IGFBP-1 and CXCL13 levels." (PMID 41562619, 2026).
benign breast disease (1 paper, 2019). "Our findings showed that BV administration resulted in enhanced IGFBP-1 level and reduced IGF-1/IGFBP-1 ratio which both suggest that BV juice might potentially reduce IGF-dependent tumor progression toward malignancy from benign breast disease." (PMID 31752829, 2019).
bone cancer (1 paper, 2022). A primary or metastatic malignant neoplasm affecting the bone or articular cartilage. "The association of IGF-1, IGFBP-1, IGFBP-3 and IGF-1R with bone cancer different features." (PMID 36713521, 2022).
bone tumor (1 paper, 2022). "The elevated level of IGFBP-1 was detected in patients with bone tumors (38.47 ± 1.15) compared to healthy subjects (32.48 ± 1.55) (P=0.007)." (PMID 36713521, 2022).
bronchopulmonary dysplasia (1 paper, 2012). Bronchopulmonary dysplasia is a chronic respiratory disease that results from complications related to lung injury during the treatment of infant acute respiratory distress syndrome in low-birth-weight premature infants or from abnormal lung development in older infants. "Mean (SD) IGF-II, IGFBP-1, IGFBP-3 and ALS levels at postmenstrual age (PMA) 30-33 weeks are shown for infants with and without bronchopulmonary dysplasia (BPD)." (PMID 22924869, 2012).
Cachexia (1 paper, 2019). Severe weight loss, wasting of muscle, loss of appetite, and general debility related to a chronic disease. "Igf1 modifiers that are co‐regulated during toxin‐induced weight loss (Igfbp1, Igfbp2, and Igfals) are also worthy of consideration as druggable targets in cachexia." (PMID 30782979, 2019).
cardioembolic stroke (1 paper, 2023). "Regarding IGFBP-1 after 3 months, it was associated with mortality in cardioembolic stroke (crude HR 3.80, 95% CI 1.32–10.9, and adjusted HR 4.76, 95% CI 1.42–16.0) and cryptogenic stroke (crude HR 5.29, 95% CI 1.27–22.0, and adjusted HR 5.53, 95% CI 1.12–27.3)." (PMID 37298072, 2023). "In contrast, 3-month s-IGFBP-1 was increased in small artery occlusion and cardioembolic stroke (p < 0.01 and p < 0.05, respectively, vs. the control group)." (PMID 37298072, 2023).
colitis (1 paper, 2023). Inflammation of the colon. "However, even though Prx4 deficiency is protective overall against colitis, there was upregulation of proteins positively associated with gastrointestinal inflammation, namely, Serpin F1, M-CSF, and IGFBP-1." (PMID 36978925, 2023).
colon carcinoma (1 paper, 2014). "It upregulates a protective factor, insulin like growth factor binding protein 1 (IGFBP1); its mRNA is upregulated in HT29 colon carcinoma cells exposed to pyridoxal (a form of vitamin B6)." (PMID 25202454, 2014).
Crohn disease (1 paper, 2022). A gastrointestinal disorder characterized by chronic inflammation involving all layers of the intestinal wall, noncaseating granulomas affecting the intestinal wall and regional lymph nodes, and transmural fibrosis. "Notably, the IGFBP1/IGFBP3 locus was recently associated by GWAS with poor prognosis in patients with Crohn’s disease, where IGFBPs have been suggested to play a role in both the inflammatory response and fibrosis." (PMID 35085231, 2022).
deafness (1 paper, 2019). An inherited or acquired condition characterized by the complete loss of the ability to hear from one or both ears. "Despite the broad concentration range of IGFBP1, a tendency was observed toward an increased concentration in patients with complete deafness, which was accompanied by a higher, though non-significantly, PAI-1/uPa ratio due to higher PAI-1 levels (data not shown)." (PMID 31293504, 2019).